TGFBR3 (transforming growth factor beta receptor 3)
Description:
Cell surface receptor that regulates diverse cellular processes including cell proliferation, differentiation, migration, and apoptosis. Initiates BMP, inhibin, and TGF-beta signaling pathways by interacting with different ligands including TGFB1, BMP2, BMP5, BMP7 or GDF5. Alternatively, acts as a cell surface coreceptor for BMP ligands, serving to enhance ligand binding by differentially regulating BMPR1A/ALK3 and BMPR1B/ALK6 receptor trafficking. Promotes epithelial cell adhesion, focal adhesion formation and integrin signaling during epithelial cell spreading on fibronectin. By interacting with the scaffolding protein beta-arrestin2/ARRB2, regulates migration or actin cytoskeleton and promotes the activation of CDC42 as well as the inhibition of NF-kappa-B. In gonadotrope cells, acts as an inhibin A coreceptor and regulates follicle-stimulating hormone (FSH) levels and female fertility (By similarity). Plays a role in the inhibition of directed and random cell migration in epithelial cells by altering the actin cytoskeletal organization. Participates in epithelial-mesenchymal transformation (EMT) upon binding to BMP2 or TGFB2, by activating the PAR6/SMURF1/RHOA pathway (By similarity). (Microbial infection) May act as a receptor for human cytomegalovirus in different cell types by interacting with HCMV trimer composed of GO, GH and GL.
Synonyms: betaglycan; BGCAN
Tractability: Antibody: UniProt places it where antibodies can reach, with high confidence; its Gene Ontology location is reachable by antibodies, with high confidence; UniProt predicts a signal peptide or a membrane-spanning region. PROTAC: ubiquitination databases record sites on it; its protein half-life has been measured.
Gene: Protein-coding gene on chromosome 1 (91,680,343 to 91,906,335, reverse strand). Ensembl gene ENSG00000069702.
Subcellular location: Cell membrane; Secreted; Secreted, extracellular space, extracellular matrix
Subcellular location (Human Protein Atlas): Cytosol; Predicted to be secreted
Pathways (Reactome):
Signal Transduction: FGFR1b ligand binding and activation; FGFR1c ligand binding and activation; Signaling by Activin; Signaling by BMP; TGF-beta receptor signaling activates SMADs; TGFBR3 PTM regulation; TGFBR3 expression; TGFBR3 regulates FGF2 signaling; TGFBR3 regulates TGF-beta signaling; TGFBR3 regulates activin signaling
Gene Ontology:
Molecular function: BMP binding; coreceptor activity; protein binding; SMAD binding; transforming growth factor beta binding; transforming growth factor beta receptor activity; transforming growth factor beta receptor activity, type III; transmembrane signaling receptor activity; type II transforming growth factor beta receptor binding; glycosaminoglycan binding; heparin binding; PDZ domain binding; transforming growth factor beta receptor binding; activin binding; fibroblast growth factor binding
Biological process: BMP signaling pathway; cardiac epithelial to mesenchymal transition; epithelial to mesenchymal transition; immune response; intracellular signal transduction; negative regulation of canonical NF-kappaB signal transduction; negative regulation of cell migration; negative regulation of extracellular matrix assembly; negative regulation of SMAD protein signal transduction; positive regulation of cell migration involved in sprouting angiogenesis; positive regulation of gene expression; positive regulation of SMAD protein signal transduction; response to follicle-stimulating hormone; response to luteinizing hormone; response to prostaglandin E; transforming growth factor beta receptor signaling pathway; cardiac muscle cell proliferation; cell migration; definitive erythrocyte differentiation; definitive hemopoiesis; epicardium-derived cardiac fibroblast cell development; heart morphogenesis; heart trabecula formation; heart trabecula morphogenesis; liver development; and 20 more
Cellular component: external side of plasma membrane; extracellular exosome; extracellular region; inhibin-betaglycan-ActRII complex; plasma membrane; receptor complex; basolateral plasma membrane; cell surface; cytosol; membrane
Genetic constraint (gnomAD): Loss-of-function variants: 44 observed, 89 expected, observed/expected ratio (o/e) 0.49, 90% interval 0.39 to 0.64. The upper end of that interval is the gene's LOEUF score, 0.64, which puts it in group 2 of 6, group 1 being the genes least tolerant of losing a copy. Missense variants: 860 observed, 1,080.9 expected, observed/expected ratio (o/e) 0.8, 90% interval 0.75 to 0.84. Synonymous variants: 378 observed, 408.87 expected, observed/expected ratio (o/e) 0.92, 90% interval 0.85 to 1.01.
Homologues: Orthologues: chimpanzee TGFBR3 (99% identical), macaque TGFBR3 (98% identical), dog TGFBR3 (90% identical), rabbit TGFBR3 (87% identical), pig TGFBR3 (85% identical), guinea pig TGFBR3 (84% identical), rat Tgfbr3 (82% identical), mouse Tgfbr3 (81% identical), tropical clawed frog tgfbr3 (59% identical), zebrafish tgfbr3 (48% identical). Paralogues in human: ENG (20% identical), TGFBR3L (8% identical).
Diseases named in the same sentence as TGFBR3 in open-access papers:
TGFBR3 is named in the same sentence as 146 diseases in open-access papers, as found by Europe PMC text mining. Sharing a sentence is not in itself a finding about the gene and the disease. The quoted sentences say what the papers report.
breast carcinoma (24 papers, 2010 to 2025). "In breast cancer and melanoma, loss of TGFBR3 in dendritic cells results in altered Treg cell infiltration and the suppression of antitumor immunity, indicating its potential role in the tumor immune microenvironment." (PMID 31803141, 2019). "In breast cancer, decreased TGFBR3 expression was correlated with the loss of heterozygosity of its gene locus and was associated with shorter recurrence-free survival and enhanced tumor invasion, metastasis, and angiogenesis." (PMID 31803141, 2019). "TGFBR3, a receptor for TGF‐β, is implicated in various cancers, including breast cancer, melanoma, prostate cancer, pancreatic cancer, colon cancer, multiple myeloma, neuroblastoma, ovarian cancer, endometrial cancer, and lung cancer." (PMID 39428382, 2024). "TGFBR3 has been confirmed as a tumor suppressor in lung cancer, pancreatic cancer, prostate cancer, and breast cancer." (PMID 36776317, 2023). "The proper localization of TGFBR3 to the basolateral membrane domain is essential for the maintenance of epithelial cell polarity and suppression of breast cancer progression." (PMID 36358747, 2022). "Apical localization of TGFBR3 can further lead to enhanced proliferation, migration, and invasion in vitro and enhanced tumorigenesis in an in vivo mouse model of breast carcinoma." (PMID 36358747, 2022). "Specifically, while ENG performed better in taxane treatments in HER2+ breast cancer subtype, TGFBR3 performed better for taxane regimens in triple-negative breast cancer (TNBC) and serous ovarian cancer." (PMID 33819300, 2021). "TGFBR3 frequently serves as a tumor suppressor in various cancer types, such as breast cancer, prostate cancer, and lung cancer." (PMID 33280236, 2021). "In prostate cancer, breast cancer, renal cell carcinoma and endometrial cancer, TGFBR3 has been identified as a tumor suppressor gene." (PMID 32931492, 2020). "Consistent with the tumor-suppressive role of these two miRNAs, TGFBR3 was reported to suppress breast cancer progression through TGF-beta signaling, and RBMS3 and PTPN14 were also shown to play roles in inhibiting metastasis." (PMID 32010179, 2019). "KRT5 combines with transforming growth factor beta receptor 3 (TGFBR3) and transcription factor JunD to promote breast cancer cell growth." (PMID 29069744, 2017). "Of interest was the effect of TGFBR3 expression correlated with improved survival at 10 years (~120 months) in all breast cancer patients." (PMID 27827906, 2016). "Once access to fibroblast cell lines are established within breast cancer scientific community, studies focused on expression of unique domains of TGFBR3 will be possible to pursue." (PMID 27827906, 2016). "To date, the functional context of TGFBR3 remains controversial in breast cancer, where studies report both tumor suppressive and tumor-promoting functions." (PMID 27827906, 2016). "TGFBR3 inhibits breast cancer progression through TGF-beta signaling." (PMID 32010179, 2019). "The functional role of TGFBR3 is controversial in breast cancer." (PMID 27827906, 2016). "Currently there are no reports demonstrating the role of TGFBR3 in the tumor microenvironment, despite the possibility that TGFBR3 controversy in breast cancer might be influenced by tumor microenvironment." (PMID 27827906, 2016). "One possibility for the conflicting role of TGFBR3 in breast cancer might be the influence of the tumor microenvironment." (PMID 27827906, 2016). "In summary, a shift in the expression pattern of BMPs in breast cancer, including increased BMP8A, BMPR1B and decreased BMP6, BMP7, ACVR1C, TGFBR2, TGFBR3 and BMPR2 presented a subtype specific role." (PMID 37333824, 2023). "The present study aimed to analyze the differential expression of genes related to growth factors such as FGF2, FGFBP1, TGFA, TGFBR3, and IGF1R in a radiation- and estrogen-induced experimental breast cancer model." (PMID 36430763, 2022).
breast carcinoma (continued). "We next examined individual genes and find that in luminal A breast cancers ENG, TGFBR3, INHA, and INHBA, were better performing as compared to INHBB particularly for taxane or anthracycline based chemotherapy regimens." (PMID 33819300, 2021). "INHA, INHBA, TGFBR3, and ENG also predicted patients’ response to anthracycline and taxane therapy in luminal A breast cancers." (PMID 33819300, 2021). "We further looked at correlations of TGFBR3 expression and RFS within molecular subtypes of human breast cancer." (PMID 27827906, 2016). "At least four well-known breast cancer genes including SMAD2, SMAD4, TGFB3 and TGFBR3 are involved in palate development." (PMID 23281707, 2012). "The implication of TGFBR3 in the inhibition of the NF-κB pathway and cellular migration via the interaction with β-arrestin 2 has also been demonstrated in MCF10A breast epithelial and MDA-MB-231 breast cancer cells." (PMID 36358747, 2022). "In summary INHA, INHBA, TGFBR3, and ENG display clear discrepant profiles of expression among responders and non-responders to both anthracycline and taxane chemotherapy for distinct breast cancer subtypes, specifically luminal A, and serous ovarian cancer." (PMID 33819300, 2021). "Interestingly, examining expression revealed that in the same luminal A breast cancers INHA, ENG and INHBA are less expressed in responders to pharmacological treatment while TGFBR3 is more expressed in these responder groups." (PMID 33819300, 2021). "We show that TGFBR3 is absent in breast cancer stroma (fibroblasts), and that this correlates with increased cytokine expression." (PMID 27827906, 2016). "Furthermore, the results suggest that all these markers should be used in the earlier stages of the disease, since an analysis of BRCA patients indicated that the FGF2, FGFBP1, TGFA, TGFBR3, and IGF1R gene expression levels were present in late stages 3 and 4 of breast cancer." (PMID 36430763, 2022). "In addition, the cell surface receptor category includes transforming growth factor-beta receptor genes (TGFBR1 and TGFBR3), and that the elevated TGFBR levels could induce collagen expression in metastatic breast cancer cells." (PMID 32315343, 2020). "In addition, restoring the expression of TGFBR3 could result in the inhibition of invasion ability of tumor cells in vitro, as well as angiogenesis and metastasis in vivo through the inactivation of the TGF-β signaling pathway in breast cancer cells." (PMID 31307515, 2019). "Our analysis of stromal changes between non-metastatic and metastatic canine mammary carcinomas highlighted molecular differences in the tumour microenvironment, including changes in VIT, TGFBR2, TGFBR3, LTBP4 and SFRP1." (PMID 37391533, 2023).
lung carcinoma (17 papers, 2014 to 2024). "Reduced or loss of TGFBR3 expression has been observed in many types of cancer, such as prostate, pancreatic, breast, renal, and lung cancer." (PMID 24968068, 2014). "Liu and colleagues found that miR-223 promotes proliferation, migration, and invasion of A549 and SPC-A1 lung cancer cells by targeting Transforming Growth Factor Beta Receptor 3 (TGFBR3)." (PMID 39125761, 2024). "Reports showed that miR-223-3p regulated the proliferation and migration of lung cancer cells by targeting the human transforming growth factor β receptor 3 (TGFBR3)." (PMID 36276078, 2022). "ADAMTS9-AS2 transfection increased TGFBR3 mRNA and protein expressions in lung cancer cells, but miR-223-3p transfection significantly suppressed TGFBR3 expression." (PMID 34819148, 2021). "MiR-223-3p promotes proliferation, migration, and invasion of lung cancer cells by targeting TGFBR3." (PMID 34819148, 2021). "miR-223-3p targeted TGFBR3 to enhance the ability of proliferation, migration, and invasion of lung cancer." (PMID 32149133, 2020). "A recent study suggested that upregulated ADAMTS9-AS2 inhibits lung cancer progression and promotion of TGFBR3 via suppression of miR-223-3p." (PMID 31637209, 2019). "They came to a conclusion that DAMTS9-AS2, TGFBR3, and miR-223-3p might provide potential therapeutic targets in lung cancer." (PMID 32149133, 2020). "Overexpression of Hmga2 titrates away has-let-7s from Tgfbr3, freeing and increasing Tgfbr3 to triggerAgo2 and TGF-β signaling pathway activity, eventually leading to lung cancer progression." (PMID 26872371, 2016). "Indeed, HMGA2 functions as a ceRNA, competing with the transforming growth factor beta receptor 3(TGFBR3) for let-7, thus allowing for the heightened expression of TGFBR3 and subsequent lung cancer progression." (PMID 26123544, 2015). "Additionally, in lung cancers, INHA and ENG differed from TGFBR3, as INHA (HR = 1.26, p = 0.00029) and ENG (HR = 1.20, p = 0.0056) were both negative predictors of survival while TGFBR3 (HR = 0.65, p = 3.4E-7) was a strong positive predictor of survival." (PMID 33819300, 2021).
pancreatic cancer (13 papers, 2017 to 2024). "The miR-107 in pancreatic cancer is associated with increased incidence and poor prognosis and may be involved in the possibility of metastasis and invasion through the TGFBR3 regulatory pathway." (PMID 34434493, 2021). "HELLS also promotes the development of pancreatic cancer through epigenetic silencing of the tumor suppressor TGFBR3, whereas inhibition of HELLS slows tumor growth and increases sensitivity to the chemotherapeutic agent cisplatin." (PMID 35774795, 2022). "RNA‐seq, ChIP, and functional assays were used to explore the downstream mechanisms of HELLS and found that the tumor suppressor TGFBR3 was responsible for HELLS knockdown‐mediated effects in pancreatic cancer cells." (PMID 33280236, 2021). "TGFβ receptor 3 (TGFBR3) is generally considered as a tumor-suppressor and restrains migration and metastasis in several types of cancer, including pancreatic cancer." (PMID 32756339, 2020). "Recently, it was noted that TAMs play a part in downregulating TGFBR3 expression in pancreatic cancer." (PMID 32756339, 2020). "In pancreatic cancer, TGFBR3 is the target of exosomal miR-501-3p and inhibits tumor formation and metastasis." (PMID 31803141, 2019). "Seven genes were identified in mass spectrometry and bioinformatic analysis, all significantly downregulated in pancreatic cancer (GEO data, GSE32676), including TSPYL2, TSR1, METAP2, CYR61, EBF2, CIRBP, and TGFBR3." (PMID 38015024, 2024). "Mechanistically, HELLS overexpression inhibited transcriptional expression of the tumor suppressor TGFBR3 in this model, and downregulation of HELLS in pancreatic cancer cells led to re-expression of TGFBR3." (PMID 36012581, 2022). "sEVs secreted by TAMS downregulate TGFbR3 by activating the TGF-β signaling pathway and promote angiogenesis in distant organs to provide an environment suitable for the survival of pancreatic cancer tumor cells." (PMID 34980146, 2022). "On the other hand, TAM could promote tumor cell growth through the inhibition of transforming growth factor beta receptor III (TGFBR3), a member of the TGF-beta superfamily coreceptor that functions as a tumor suppressor in pancreatic cancer." (PMID 35644825, 2023). "The first extensive study in cancer about the role of TGFBR3 in EMT revealed that the deprivation of TGFBR3 expression can lead to increased invasion and migration of the pancreatic cancer cells PANC-1 without affecting Snail or E-cadherin levels." (PMID 36358747, 2022).
pancreatic ductal adenocarcinoma (10 papers, 2019 to 2025). An infiltrating adenocarcinoma that arises from the epithelial cells of the pancreas. "Exosomal miR-501-3p produced by TAMs was reported to contribute to the development of pancreatic ductal adenocarcinoma (PDAC) by inhibiting the TS transforming growth factor beta receptor 3 (TGFβR3)." (PMID 36189271, 2022). "Another study showed that macrophage-derived exosomal miR-501-3p can inhibit the expression of the tumor suppressor TGFBR3 and promote the development of pancreatic ductal adenocarcinoma, providing a new target for the molecular therapy of pancreatic ductal adenocarcinoma." (PMID 34266418, 2021). "Conversely, M2-like TAMs-derived exosomes could facilitate HCC metastasis by transferring αmβ2 integrin to tumor cells, and TAMs exosomal microRNA-501-3p contributes to the progression of pancreatic ductal adenocarcinoma through the TGFBR3-mediated TGF-β signaling pathway." (PMID 35607322, 2022). "In pancreatic ductal adenocarcinoma, TAM-derived EVs transferred miR-501-3p to inhibit expression of the tumor suppressor TGFBR3 gene, thus stimulating tumor growth and invasion." (PMID 37770932, 2023). "TAM-derived exosomal miR-501 promotes progression of pancreatic ductal adenocarcinoma by inhibiting the tumor suppressor, TGF-beta Receptor III (TGFBR3) gene and activating the TGF-β signaling pathway." (PMID 35805995, 2022). "For example, miR-501-3p loaded by M2-derived exosomes has been shown to downregulate TGFBR3, thus activating the TGF-β signaling pathway and promoting the progression of pancreatic ductal adenocarcinoma." (PMID 33330451, 2020). "Furthermore, TGFBR3 is involved in the activation of the TGF-β signaling pathway, and TGFBR3 is downregulated in pancreatic ductal adenocarcinoma cells." (PMID 35087950, 2021).
prostate carcinoma (9 papers, 2013 to 2024). A carcinoma that arises from epithelial cells of the prostate gland. "For example, TGFBR3 was found to be downregulated in prostate cancer via a loss of heterozygosity at its encoding genomic locus and epigenetic regulation." (PMID 31803141, 2019). "The up-regulation of TGFBR3 expression significantly attenuates the motility and invasion in vitro and tumor formation in vivo of prostate cancer cells." (PMID 31307515, 2019). "Also of interest were several genes associated with prostate cancer metastases including FOXA1, EZH2, SCHLAP1, CDH1, SOX4, SOX9, HOXB13, and TGFBR3." (PMID 38067373, 2023). "Previous studies have shown that TGFBR3 produces anticancer activities via regulating invasion, proliferation, cell migration and angiogenesis and that expression of TGFBR3 is decreased in a variety of malignancies such as breast, kidney, lung, ovary, pancreas and prostate cancers." (PMID 23387308, 2013). "Module 2 includes TGFBR3, FOXO1, RSPO3, PLAG1, and CYLD, which have been shown to play a role in mediating or inhibiting prostate cancer progression." (PMID 39347576, 2024).